SATL1 (spermidine/spermine N1-acetyl transferase like 1)
Tractability: No criterion of Open Targets' tractability assessment is met for any kind of drug.
Gene: Protein-coding gene on chromosome X (85,092,284 to 85,243,911, reverse strand). Ensembl gene ENSG00000184788.
Subcellular location (Human Protein Atlas): Nucleoplasm; Cytosol
Gene Ontology:
Molecular function: diamine N-acetyltransferase activity; spermidine binding; acyltransferase activity, transferring groups other than amino-acyl groups
Biological process: polyamine metabolic process
Homologues: Orthologues: macaque SATL1 (87% identical), chimpanzee SATL1 (63% identical), rat Satl1 (37% identical), mouse Satl1 (35% identical), tropical clawed frog satl1 (15% identical), dog SATL1 (12% identical), Drosophila melanogaster CG4210 (8% identical), Caenorhabditis elegans D2023.4 (6% identical). Paralogues in human: SAT1 (15% identical), SAT2 (10% identical).
Diseases named in the same sentence as SATL1 in open-access papers:
SATL1 is named in the same sentence as 7 diseases in open-access papers, as found by Europe PMC text mining. Sharing a sentence is not in itself a finding about the gene and the disease. The quoted sentences say what the papers report.
pneumonia (1 paper, 2025). An acute, acute and chronic, or chronic inflammation focally or diffusely affecting the lung parenchyma, caused by an infection in one or both of the lungs (by bacteria, viruses, fungi, or mycoplasma.). "Firstly, high thoracic muscle area but not abdominal muscle area, high SATL1 and low ACL1 are independent protective factors against admitted to the MICU in sepsis patients with pneumonia." (PMID 41211659, 2025).
cancer (1 paper, 2014). A tumor composed of atypical neoplastic, often pleomorphic cells that invade other tissues. "Only C8orf74 exhibited no measurable expression in cancer cells / tissues (although C1orf141, HEATR7B and SATL1 could not be analysed via meta-analyses due to their absence on the arrays)." (PMID 25594029, 2014).
SATL1 also shares sentences with these, for which no sentence is quoted: autism spectrum disorder (1 paper); heart failure (1); prostate carcinoma (1); Sepsis (1); tumor (1).